RAB32 (RAB32, member RAS oncogene family)
Diseases named in the same sentence as RAB32 in open-access papers (continued):
Sharing a sentence is not in itself a finding about the gene and the disease.
infection (continued). "RAB32 is also recruited to pathogen-containing vacuoles as part of a host defence mechanism during infection with Salmonella, Legionella, or Trypanosoma; this relies on RAB32 orchestrating the delivery of the mitochondrial metabolite itaconate to the vacuolar lumen." (PMID 41038817, 2025). "In contrast, the combination of SopD2 and GtgE Salmonella at the SCV membrane during infection guarantees fast Rab32-inactivation as a results of a series of rapid enzymatic steps: Rab32:GDP is likely recruited to the SCV via a GEF (BLOC-3) from its cytosolic complex with GDI promptly." (PMID 29298974, 2018). "Therefore, these effectors act in effect redundantly to block Rab32 trafficking and facilitate the establishment of a systemic infection in the mouse." (PMID 27645564, 2018). "Less is known about the impact of Salmonella on the host endosomal pathway at later stages of infection, although two SPI-2 effectors, SopD2 and GtgE are known to target Rabs including Rab32." (PMID 32974215, 2020). "Consistent with the observed Rab32 which is upregulated in time course experiments; similar results were observed when MOI dependency was tested at 2 h post-infection." (PMID 31199852, 2019). "All together our results indicate that the BRAM pathway is not controlled by neither Rab9 nor VARP suggesting that that Rab32 is controlled through a different regulation circuit during infection." (PMID 33392103, 2020). "However, we also noticed that a portion of Rab32-positive phagosomes are free of late endosomal markers (LAMP1 and LAMP2) and late endosomal/lysosomal probe (Lysotracker) from 1 to 6 h after infection, suggesting that not all Rab32-positive phagosomes are fused with late endosomes." (PMID 31199852, 2019).
tumor (11 papers, 2008 to 2025). "Elevated expression of RAB32 has been associated with enhanced tumor cell proliferation and invasion, while higher levels of RAB32 have been statistically correlated with poorer patient outcomes in HCC19." (PMID 39668831, 2024). "The immunoassay results showed that RAB32 expression was correlated with immune infiltration of the tumor microenvironment." (PMID 39668831, 2024). "Using the ESTIMATE algorithm score to predict tumor purity, we found that tumor tissues with high RAB32 expression harbored more stromal and immune cells than those with low RAB32 expression, with the ESTIMATE score also being higher." (PMID 39668831, 2024). "First, we used the cBioPortal database to study the gene copy number variation of RAB32, observed the genetic changes in RAB32 in all different tumor samples of TCGA, and found that the "deep deletion" type was the main type of cancer, including GBM." (PMID 39668831, 2024). "Using the TISIDB database, we investigated the correlation between RAB32 mRNA expression and tumor-infiltrating lymphocytes (TILs)." (PMID 39668831, 2024). "The correlation of Rab32 expression with patient prognosis and tumor grade was investigated by public dataset analysis and clinical specimen validation." (PMID 36922509, 2023). "In order to evaluate the function of Rab32 on tumor formation in vivo, we further transplanted the GBM cells into the subcutaneous tissue of the nude mice." (PMID 36922509, 2023). "Western blotting also supported these protein changes, which revealed the necessity of Rab32 in tumor invasion and mesenchymal transition." (PMID 36922509, 2023). "Both the subcutaneous and intracranial xenograft tumor model were utilized to evaluate the effect of Rab32 on GBM in vivo." (PMID 36922509, 2023). "At 35 days post-injection, the tumor volumes of mice transplanted with Rab32-knockdown cells was significantly smaller than that with control cells." (PMID 36922509, 2023). "A recent study demonstrated that RAB32 is a mechanistic target of the rapamycin complex 1 signaling pathway, and elimination of RAB32 has been shown to decrease tumour cell viability and proliferation." (PMID 35610596, 2022). "Furthermore, to validate RAB32 expression patterns in different cancer types, we utilized the GEPIA online platform to assess RAB32 expression in tumor tissues." (PMID 39668831, 2024). "Rab32 could promote lipid metabolic reprogramming efficiency, which supported migration, invasion, and metastasis of tumor cells." (PMID 36922509, 2023). "Our analysis showed that Rab32 was more expressed in GBM compared to non-tumor samples (p < 0.05)." (PMID 36922509, 2023). "RAB32 is significantly up-regulated and acts as a tumor oncogene in various human cancers." (PMID 36539702, 2022). "Inhibition of miR-30c-5p promotes tumor progression via RAB32 in hepatocellular carcinoma." (PMID 36539702, 2022). "In conclusion, our study demonstrated that miR-141-5p played an important role in the activation of K562 cells and may act as a tumor suppressor via the targeting of RAB32 in CML." (PMID 32038235, 2019). "Taken together, our study demonstrates that miR-141-5p plays an important role in the activation of K562 cells in vitro and may act as a tumor suppressor via targeting RAB32 in the development of CML." (PMID 32038235, 2019). "Furthermore, silencing of Rab32 in vivo suppressed tumor malignancy via ERK/Drp1 axis." (PMID 36922509, 2023). "In conclusion, our findings indicate a significant upregulation of RAB32 in GBM cell lines and tumor tissues, which enhances the proliferation and invasion capabilities of GBM." (PMID 39668831, 2024). "The expression level of Rab32 is significantly elevated in the GBM, especially in the most malignant mesenchymal subtype, and is positively correlated with tumor pathological grade and poor prognosis." (PMID 36922509, 2023).
tumor (continued). "The expression levels of MYOF, Rab7, and Rab32 in tumor tissues were significantly higher than those in normal tissues, implying the co‐expression relationships between MYOF and Rab7, and between MYOF and Rab32." (PMID 33634965, 2021). "The model includes seven key genes—SNX5, YBX1, GNPD1, RAB32, TPM3, ATP6V0B, and RAB7A—which may be involved in tumor growth, immune escape, and microenvironment remodeling and may serve as potential targets for therapy." (PMID 41031219, 2025).
cancer (8 papers, 2015 to 2024). A tumor composed of atypical neoplastic, often pleomorphic cells that invade other tissues. "Rab32 silencing causes the structural destruction of mitochondrion and induced mitochondrial fragmentation, thus promoting cancer cell death." (PMID 33634965, 2021). "Collectively, data from both databases indicated a general upregulation of RAB32 expression in various cancers, including CHOL, ESCA, GBM, HNSC, KIRC, KIRP, and STAD." (PMID 39668831, 2024). "Kaplan–Meier survival analysis showed that intracranial tumor-bearing mice with Rab32 knockdown had a tendency to prolong survival time compared to the control group, indicating the contribution of Rab32 on cancer malignancy." (PMID 36922509, 2023). "Our findings, which are consistent with previous research, indicated that RAB32, SMYD3, AP2M1, and HSP90B1 were associated with cancer progression." (PMID 35610596, 2022). "RAB32 is a potential prognostic marker that is overexpressed in a variety of cancers." (PMID 39668831, 2024). "GSEA was used to analyze cancer-related signaling pathways that may be activated by high RAB32 expression." (PMID 39668831, 2024). "Notably, combined overexpression of Rab32, a protein kinase A-anchoring protein fostering the ER-mitochondrial tethering, and UCP2 caused a significant drop in cancer cells' viability." (PMID 33614647, 2021). "Mitochondrial dysfunction is strongly related to aging and cancer, and decreased expression of RAB32 may result in disrupted mitochondrial dynamics and changes in apoptotic processes which would also contribute to the development of cancer." (PMID 25807146, 2015). "Consequently, aberrant functioning of RAB32 may contribute to metabolic disorders and cancer development." (PMID 39668831, 2024). "Notably, expression levels of proteins facilitating mitochondrial-ER interaction, including AKAP1, RICTOR, Rab32, PACS2, GPR75, and PEMT1, were reduced in these cancer tissues." (PMID 33614647, 2021). "Moreover, overexpression of Rab32, a protein kinase A-anchoring protein fostering the ER-mitochondrial tethering, leads to a decline in the expression of UCP2, which points to an adaption strategy of cancer cells to escape mitochondrial Ca2+ overload-induced cell death." (PMID 33614647, 2021).
bacterial infection (4 papers, 2021 to 2025). "Furthermore, studies have found that the depletion of BLOC-3 or RAB32 limits the ability of macrophages and monocytes to resist bacterial infection." (PMID 39457053, 2024). "This suggests that Rab32 could be part of a pathway critical to control some bacterial infection in humans." (PMID 33523895, 2021). "In addition, RAB32 in HSP1 macrophages activates the mTOR signaling pathways, which impairs bacterial infection and cytokine production." (PMID 39457053, 2024).
RAB32 also shares sentences with these, for which no sentence is quoted: ovarian carcinoma (3 papers); adenocarcinoma (2); non-small cell lung carcinoma (2); bladder urothelial carcinoma (1); breast carcinoma (1); cervical cancer (1); chronic obstructive pulmonary disease (1); frontotemporal dementia (1); graft versus host disease (1); hematological malignancies (1); Hermansky-Pudlak syndrome (1); infectious disease (1); inflammatory bowel disease (1); pancreatic adenocarcinoma (1); Parkinsonism (1); periodontitis (1); renal clear cell carcinoma (1); rheumatoid arthritis (1); schizophrenia (1); synucleinopathy (1); Tremor (1); triple-negative breast carcinoma (1).